PPARA (peroxisome proliferator activated receptor alpha)
Diseases named in the same sentence as PPARA in open-access papers (continued):
Sharing a sentence is not in itself a finding about the gene and the disease.
Hepatic steatosis (continued). "A previous study under similar conditions reported that combined treatment with a PPARα agonist, fenofibrate, and an LXR agonist, T0901317, alleviated insulin resistance and improved glucose tolerance but dramatically exacerbated hepatic steatosis." (PMID 25143786, 2014). "Indeed, it has been previously shown that the lack of PPARα may cause an important hepatic steatosis and liver inflammation." (PMID 25147439, 2014). "Findings of a recent report indicated that PPARα also modulates hepatic lipogenic gene expression, such as DGAT, ACC, and PGC-1α, which are closely related to fatty acid synthesis and oxidation in hepatic steatosis in HFD-fed animals." (PMID 24905748, 2014). "PPARA positively regulates fatty acid oxidation, therefore down-regulation of PPARA and beta-oxidation-related transcripts as observed in human hepatocytes as well as in cold-exposed sea bream liver, might reduce lipid beta-oxidation with consequent lipid accumulation, leading to hepatic steatosis." (PMID 25194679, 2014). "In conclusion, in addition to the beneficial effect of decreasing Ang II production, aliskiren can activate hepatic PPARα and AMPK to reduce hepatic steatosis and oxidative stress." (PMID 24204981, 2013). "Loss of SIRT1 from hepatocytes impairs PPARα signaling, resulting in decreased fatty acid oxidation and leading to the development of hepatic steatosis on a high-fat diet, whereas overexpression of SIRT1 induces expression of PPARα gene targets." (PMID 20814433, 2010). "In hepatic steatosis and steatohepatitis, the ω-oxidation cytochrome P450 CYP4A gene expression is increased even with reduced hepatic levels of PPARα." (PMID 20300478, 2009). "During hepatic steatosis, members of CYP4 family of fatty acid ω-hydroxylase are induced even with the downregulation of PPARα, which regulates CYP4A gene expression." (PMID 20300478, 2009). "Among the factors involved in the control of hepatic steatosis by PUFA, PPARα has been considered important, even if recent data are controversial." (PMID 19046413, 2008). "Moreover, L-Phe regulates the BNIP3-mediated PPARα and AMPK/mTOR signalling pathways to promote hepatic steatosis." (PMID 40588730, 2025). "EPA-PE significantly increased PPARα protein levels in the liver of healthy mice and increased PPARα and CPT1 protein levels in the liver of rodents with insulin resistance, which alleviated hepatic steatosis and lipid accumulation." (PMID 40137162, 2025). "In summary, Overexpression of FGF15 alone, with or without a combined activation of PPARα, effectively reduces hepatic steatosis." (PMID 40815899, 2025). "CP intervention failed to improve NAFLD-related parameters in Pparα−/− mice such as body weight, epididymal adipose weight, liver TG, hepatic steatosis score." (PMID 38831430, 2024). "Sesamin can inhibit fatty acid synthesis, induce fatty acid beta oxidation, and promote the expression of genes related to cholesterol efflux and catabolism by activating the AMPK and PPARα signaling pathways, thereby alleviating lipid accumulation during NAFLD and preventing liver steatosis." (PMID 39758315, 2024). "Notably, FT enhanced theexpression of liver fatty acid β-oxidation proteins, such aspAMPK/AMPK, PPARα, and PGC-1α, suggesting its potentialto counter liver steatosis." (PMID 38965062, 2024). "SIRT1 overexpression using adenovirus can reduce PGC-1α acetylation level and induced PPARα transcriptional signalling, as well as the expression of PPARα/PGC-1α targeting genes, thereby increasing FAO, and alleviating MASLD in mice with HFD-induced hepatic steatosis." (PMID 39264516, 2024). "Additionally, this overexpression downregulates the expression of PPARα and its downstream genes carnitine palmitoyltransferase 1 (CPT1) and CPT2, highlighting another mechanism involved in the development of fatty liver disease." (PMID 39451567, 2024).
Hepatic steatosis (continued). "HFHFr males presented hypertriglyceridemia, but not hepatic steatosis, partially due to enhanced liver PPARα-related fatty acid β-oxidation and the VLDL-promoting effect of leptin." (PMID 37764693, 2023). "Together, our data suggest that fasting-induced hepatic steatosis in Hmgcs2ΔLiv mice is not driven by altered lipolysis, lipid uptake, PPARα signaling, or lipogenesis." (PMID 37503004, 2023). "However, PPARα and PPAR-γ have opposite effects on hepatic steatosis, suppressing and favoring lipogenesis, respectively." (PMID 36769165, 2023). "In comparison with the findings on wild-type mice, HDCA intervention failed to improve NAFLD-related parameters in Pparα−/− mice such as body weight, liver TG, hepatic steatosis score, and NAS." (PMID 37673856, 2023). "In accordance, Hcy/AdoHcy has already been linked to elevated LDL-cholesterol, reduced apolipoprotein A-I expression, activation of adipocyte lipolysis leading to hepatic steatosis, increased VLDL secretion, as well as decreased PPARα/γ mRNA and protein levels." (PMID 36081286, 2022). "As PPARα and PGC-1α can interact to regulate FAO in mitochondrion, which plays an important role in hepatic lipid disposal, a recent study has found that Nuciferine was beneficial to hepatic steatosis by activating the PPARα/PGC1α pathway." (PMID 35956423, 2022). "Notably, miR-122, miR-21 and miR-34a, identified as upregulated in NAFLD, play critical roles in deranged hepatic lipid metabolism and hepatic steatosis by regulating multiple hepatic pathways such as SREBP1-c, SIRT1 and PPARα." (PMID 36613525, 2022). "Moreover, MG5311 suppressed hepatic steatosis by regulating SREBP-1c and PPARα expression via upregulating the SIRT1 pathways." (PMID 36557739, 2022). "Despite specific favorable metabolic effects, PPARα activator fibrates have failed to improve hepatic steatosis or NASH in humans." (PMID 34745420, 2021). "Since PPARγ agonists induce storage of fatty acids and glucose rather than consumption in the cell, the dual activation of PPARα and PPARγ is proposed to be more beneficial in managing metabolic diseases such as dyslipidemia of diabetes and fatty liver." (PMID 34593018, 2021). "The peripherally restricted antagonist AM6545 was able to reduce hepatic steatosis and improved liver injury through PPARα as shown by its lack of activity in PPARα knockout DIO mice." (PMID 33498245, 2021). "The pathological effect of NIK in ALD may be attributed to the suppression of PPARα, the main controller of fatty acid oxidation in the liver, because PPARα agonists reversed NIK-mediated hepatic steatosis and malfunction of fatty acid oxidation." (PMID 32206109, 2020). "The finding that bilirubin may induce the PPARα pathway and increase BHOB production to control hepatic steatosis needs validated by clinical studies." (PMID 33390979, 2020). "An upstream regulator analysis indicated that PPARα and XBP1 were the top 2 predicted transcription activators involved in the process of hepatic steatosis induced by OSI-906, whereas pathways related to SREBF2 and lysophosphatidylcholine were identified in the linagliptin-treated group." (PMID 33105604, 2020). "Furthermore, MG clearly alleviated serum TG and total cholesterol release; upregulated AKT, AMPK, and PPARα expression; suppressed SREBP-1c generation; and alleviated hepatic steatosis and dyslipidemia in Ty-induced hyperlipidemia mice." (PMID 29467759, 2018). "Moreover, the immunofluorescence results also demonstrated that MG reliably activated the AMPK, AKT, and PPARα pathways and inhibited the SREBP-1c pathway in OA-induced hepatic steatosis." (PMID 29467759, 2018).
Hepatic steatosis (continued). "In addition, miR-34a inhibition increases the levels of phosphorylated AMPKα separately through mediating PPARα regulation and SIRT1 pathway to suppress the development of fatty liver." (PMID 29681936, 2018). "INS, PPARA, LEP, SREBF1, and ALB are the introduced biomarker panel for fatty liver disease." (PMID 28224024, 2016). "In contrast to PPARα activation, AMPK phosphorylation suppresses the activity of the key proteins involved in lipogenesis, such as SREBP-1c and HMGCR, and improves liver steatosis." (PMID 26168156, 2015). "The PPARδ-stimulated hepatic fatty accumulation we observed in our study was accompanied by substantial weight loss, if not preceded, with exceptions of PPARα-KO and PPARδ-KO mice fed GW501516, where neither weight loss nor liver steatosis was observed." (PMID 26604919, 2015). "However, during hepatic steatosis and steatohepatitis, CYP4A (a member of fatty acid ω-hydroxylase family) can be induced even with the down-regulated PPARα, as recently described." (PMID 24146933, 2013). "As opposed to PPARγ, the role of PPARα to prevent hepatic steatosis, likely by favoring fatty acid oxidation, is supported by a number of studies." (PMID 23024649, 2012). "It has been shown that mice lacking PPARα exhibit hepatic steatosis, hypoglycemia, and myocardial lipid accumulation." (PMID 23243438, 2012). "Here, we found that RGZ treatment increased adiponectin, PPARα, PPARγ and AMPK activation, suggesting that these factors may be involved in the RGZ-mediated amelioration of hepatic steatosis." (PMID 21373642, 2011). "In the absence of PPARα, liver steatosis and inflammation are enhanced in mice chronically fed a HFD." (PMID 20936127, 2010). "The ability of PPARα to stimulate fatty acid oxidation and suppress hepatic inflammation has led to the exploration of PPARα agonists as a therapeutic option for nonalcohol fatty liver disease and specifically nonalcoholic steatohepatitis (NASH)." (PMID 20936127, 2010). "While down-regulation of DGAT1 in spheroids following LGALS3 silencing could have protective effects in condition of hepatic steatosis, changes in CPT1A and PPARA mRNA levels, might be a consequence of the lipid content reduction or represent an independent effect exerted by Gal-3." (PMID 40608687, 2025). "Thus, the change in PPARα and its target genes could explain the alleviating effect of aerobic exercise on HFD-induced liver steatosis." (PMID 41223206, 2025). "Furthermore, this study found that CB1 co-evolved with PPARα, and blocking CB1 did not ameliorate hepatic steatosis in mice with hepatic PPARα deficiency." (PMID 38397045, 2024). "These enzymes are regulated by the transcription factor PPARα; however, it is not clear if mitochondrial oxidative enzymes lead to hepatic steatosis since normal, increase or decrease of fatty acid oxidation in subjects with hepatic steatosis has been demonstrated." (PMID 39203731, 2024). "It should be noted that vitamin D protects against NAFLD, ameliorating hepatic steatosis owing to obesity-induced dyslipidemia, by reducing plasma lipid uptake through fatty acid translocase (FAT/CD36) and increasing hepatic mitochondrial β-oxidation via the PPARα signaling pathway." (PMID 39404394, 2024). "A previous study shows that lack of Pparα in hepatocytes may spontaneously trigger liver steatosis, suggesting that hepatic steatosis may worsen in those with NASH." (PMID 37894124, 2023). "Indeed, the PPARγ agonist pioglitazone and PPARα fenofibrate reduced atherosclerosis and hepatic steatosis in mice lacking both ApoE and Farnesoid x receptor (FXR), which modeled NASH and atherosclerosis simultaneously." (PMID 37200978, 2023). "Interestingly, neither FABP upregulation nor hepatic steatosis occurred after in ovo silencing of PPARα." (PMID 38133352, 2023).
Hepatic steatosis (continued). "In previous studies using HFD animal models, dietary KO ameliorates the hepatic steatosis and dyslipidemia through AMPK activation, and the oral gavage improves metabolic alterations in the liver through a modification of lipid synthesis-related gene expressions (i.e., PPARα, SREBP1c, and FAS)." (PMID 36005486, 2022). "In addition, CGX administration significantly reduced hepatic steatosis, via modulation of lipolytic and lipogenic molecules, including activated adenosine monophosphate activated protein kinase (AMPK) and peroxisome proliferator activated receptor-alpha (PPARα)." (PMID 36105183, 2022). "In addition, PPARα knockout (PPARαKO) male but not female mice die with massive hepatic steatosis after treatment with etoxomir, an inhibitor of hepatocellular FA flux; in PPARαKO males, estradiol pre-treatment reduces etomoxir-induced mortality to 20%." (PMID 34572151, 2021). "During fasting, hepatocyte PPARα disruption could not adjust liver metabolism to excess FA release from adipose tissues, resulting in aggravation of hepatic steatosis." (PMID 32192216, 2020). "Additionally, hepatic steatosis (fatty liver group) led to a lower protein abundance of SIRT1 related transcription factors PGC-1α and peroxisome proliferator-activated receptor alpha (PPARα) (p < 0.05 or p < 0.01)." (PMID 32230804, 2020). "Interestingly however, exercise-trained GCN2KO mice were better protected against hepatic steatosis with downregulated expressions of p-eIF2α and ATF4, upregulated expressions of p-AMPK and SIRT1, and the presence of PPARα in the liver, compared to the exercised WT mice." (PMID 33299856, 2020). "Furthermore, in addition to the FXR-SHP-SREBP-1c cascade, these FXR-ligand treatments significantly inhibited SREBP-1c-related lipogenesis, but did not activate PPARα-related catabolism in the mouse fatty liver model." (PMID 30936623, 2019). "Previous studies demonstrated that the lack of PPARα aggravated hepatic steatosis in HFD-fed mice." (PMID 31744059, 2019). "Alisol B 23-acetate intervened the downstream regulators of FXR such as SREBP1c, PPARα, and genes involved in triglyceride metabolism (ApoC-II, ApoC-III, and angiopoietin like ANGPTL3), contributing to the improvement of hyperlipidemia as well as hepatic steatosis." (PMID 31275407, 2019). "Similarly, these mice are also susceptible to diet-induced NASH: although high-fat feeding does normally not lead to NASH, it does induce hepatic steatosis and inflammation in mice lacking PPARα." (PMID 28159867, 2017). "Without PPARα, the expression levels of its target genes, including Fgf21, do not increase after birth, which promotes the build up of fats in liver cells, a condition known as liver steatosis." (PMID 27367842, 2016). "Lipid measurements revealed no liver steatosis in PPARα-KO mice treated with PPARδ ligand." (PMID 26604919, 2015). "Based on the evidence obtained from previous studies, we hypothesized that PPARα activation induces, rather than improves, hepatic steatosis." (PMID 24926685, 2014). "Clinical studies have reported that PPARα activation does not improve hepatic steatosis." (PMID 24926685, 2014). "Although palmitoleic acid did not improve hepatic steatosis, this ω-7 fatty acid reduced the serum aspartate transaminase levels in both WT and PPARα-knockout mice, which indicates that the observed reduction in liver damage is independent of PPARα." (PMID 25147439, 2014). "In the present study, we showed that fenofibrate treatment increased hepatic steatosis and the liver triglyceride content through the up-regulation of mature SREBP-1c (a key lipogenic transcription factor) expression via the direct binding of PPARα to the DR1 motif of the SREBP-1c gene." (PMID 24926685, 2014).
Hepatic steatosis (continued). "The improvement of hepatic steatosis and presumably inflammation is likely due to activation of GLP-1R on hepatocytes, because others have shown that exenatide stimulates hepatocyte expression of PPARα and PPARγ that improve hepatic fatty acid oxidation, lipid export, and insulin sensitivity." (PMID 24188631, 2013). "In addition, mice lacking PPARα−/−, which develop liversteatosis, also expressed high hepatic PPARγ mRNA." (PMID 19390649, 2009). "Besides, studies have reported that inhibition of miR-34a may increase the levels of its downstream targets, including peroxisome proliferator-activated receptor-α (PPARα) and Sirtuin protein family-Sirtuin1 (SIRT1) that were related to fatty acid oxidation thereby alleviating liver steatosis." (PMID 41223206, 2025). "When the activation of PPARα signaling is impaired by fructose overdose, the cooperative induction of lipid catabolic genes and suppression of lipogenic genes by HNF4α and GR may play a key role in the early resistance to HFHS-induced fatty liver and hyperlipidemia (Graphical abstract)." (PMID 35614477, 2022). "In addition, the higher circulating FFAs with KrO may result in a higher influx of fat to the liver, thereby counteracting the beneficial effects on hepatic fat oxidation (i.e., PPARA, ACOX1, PPARGC1A), altogether leading to comparable hepatic steatosis as in the HFD controls." (PMID 34444996, 2021). "In contrast, treatment with a Pparα agonist in HFD-fed USP25 KO mice did not alleviate metabolic phenotypes or hepatic steatosis, as confirmed by histological analysis, likely due to decreased Pparα levels." (PMID 39395794, 2024). "However, in this study, we found that a PPARα agonist could not ameliorate diet-induced hepatic steatosis in Usp25−/− mice, which was inconsistent with the findings of previous studies showing that a PPARα agonist could ameliorate diet-induced hepatic steatosis in wildtype mice." (PMID 39395794, 2024). "Therefore, our data indicated that pharmacological activation of PXR might induce hepatic steatosis through the stimulation of PXR-PPARγ and inhibition of fatty acid β oxidation by regulating PPARα pathways rather than alterations on SREBP1 signaling pathways." (PMID 35966089, 2022). "Thus, it is highly possible that hepatic steatosis phenotype in HFD-fed RORαLKO mice may be resulted from both upregulated PPARγ activation and suppressed PPARα transcriptional activity in the absence of RORα." (PMID 28757615, 2017).